GZMA (granzyme A)
Diseases named in the same sentence as GZMA in open-access papers (continued):
Sharing a sentence is not in itself a finding about the gene and the disease.
tumor (continued). "GZMA from the NK cell and CTLs were proven to induce pyroptosis in murine tumor cells via the cleavage of GSDMB, which not only enhances the antitumor immunity but also promotes tumor clearance." (PMID 36119049, 2022). "The results from HPA database showed that the immunohistochemical staining intensity of SDHB, GZMA, BTK, EEF2K, and NR1H2 in glandular cells of normal tissues was stronger than tumor cells, demonstrating that these genes were significantly expressed in normal colon tissues than in tumor tissues." (PMID 35912258, 2022). "Moreover, GZMA-derived natural killer cells and CTLs can directly cleave GSDMB and trigger pyroptosis in cancer cells, leading to tumor clearance in a mouse model." (PMID 35990696, 2022). "In single-cell RNA-seq data, we found that, in some patients, the glutamine metabolism gene scores of tumor cells were significantly higher than those of CD8T cells, while decreased ratios of CD8-Tef-GZMA and suppressed tumor-killing activity of CD8-Tef-APOC2 were observed." (PMID 36497182, 2022). "Importantly, the majority of cells in cluster 5 were from P-LN and tumor 3, and they exhibited high expression of GNLY, CD69, and GZMA, indicating that they were closely related to immune cells." (PMID 36569924, 2022). "For instance, our results support the finding that the saliva peptidome is a pool of products generated by peptidases whose origin is in the oral microflora (e.g., bacteria glutamine protease), host salivary glands, immune cells (e.g., proteasix predicted granzyme A, GZMA), and tumor cells." (PMID 33578082, 2021). "For instance, a study demonstrated that GSDMB induced by lymphocyte-derived granzyme A (GZMA) could trigger the pore-forming activity and pyroptosis, thus promoting anti-tumor immunity." (PMID 34731088, 2021). "Upregulated within the tumor-infiltrating CD4+ T cells were heat shock proteins (HSPA1A and HSPA1B), Jun and FOS constituents (FOS, JUN, and JUNB), MHC-II molecules (HLA-DRB), and secreted molecules (CCL5, GZMA, and GZMK)." (PMID 33504936, 2021). "For CD8+ T cells, although the cytotoxic molecules (GZMA, GZMB, NKG7, and PRF1) were highly expressed, a fraction of CD8+ T cells showed positive with exhaustion biomarkers (CTLA4, PDCD‐1, and TIGIT), indicating their tumor‐cytotoxic activity was constrained." (PMID 34185421, 2021). "Therefore, the CYT score based on GZMA and PRF1 expression levels is considered a rational method to reflect the activity of tumor‐infiltrating CD8+ T cells and the antitumor immune response." (PMID 33769705, 2021). "CYT quantified the cytolytic activity of the local immune infiltrate based on transcript levels of two key cytolytic effectors, granzyme A (GZMA) and perforin (PRF1), which represented the process of killing cancer cells that tumor immunotherapy strategies aim to boost." (PMID 33915876, 2021). "The increased expression of cytotoxic effector molecules GZMA, GZMB, GZMH, GZMM, GNLY, NKG7, and PRF178 but also of the thioredoxin function inhibitor TXNIP79, demonstrates a potent effector capacity to eliminate malignant cells and suppress tumor growth." (PMID 33602930, 2021). "In addition, we observed enhancement of not only CD8+ T cell infiltration but also DC infiltration and upregulation of CXCL9, CXCL10, GZMA, GZMB, and IFN-γ in Col6a1−/− tumor tissues compared with WT MCA205 tumor tissues." (PMID 34782761, 2021). "We also measured perforin (PRF1) and granzyme A (GZMA) gene expression as representations of cytolytic activity (CYT) in tumors and found that CYT was inversely correlated with tumor stages across all cancer types (n = 6,458, 25 tumor types)." (PMID 34698427, 2021). "Despite these differences, markers of cytotoxic response, such as granzyme A and B, perforin, and RORγT as assessed by qRT-PCR quantifications, were not significantly enhanced in tumor tissues." (PMID 34804993, 2021).
tumor (continued). "Both subsets of CD8+ T cells from tumor samples expressed higher effector genes than nonmalignant samples, including chemokines (e.g., CCL5), cytotoxicity-associated genes (PRF1, GZMA, GZMB, GZMH), and proinflammatory cytokines (e.g., IL-32)." (PMID 34921160, 2021). "However, on the other side, GzmA released by NK cells, T cells and CAR-T cells mediates anti-tumor activity in different gasdermin B-positive murine models through pyroptosis." (PMID 34685542, 2021). "Tumor CD8+ T cells expressed significantly less granzyme A (GZA), B (GZB), and PD-1 than those in adjacent non-cancerous tissues and also had significantly lower cytotoxic killing of allogeneic target cells." (PMID 33968059, 2021). "Furthermore, we found a strong correlation of TIL score with the expression of the cytolytic marker genes GZMA and PRF1 indicating an abundance of CTLs and NK cells in these tumor samples." (PMID 33980253, 2021). "As for T cell related cytotoxins, essential in tumor killing, stacked FPKM of 8 genes (PRF1, GZMM, GZMK, GZMH, GZMB, GZMA, FASLG, and FAS) demonstrated that these genes were more highly expressed 1.7-fold (P = 0.037) in IFNγ positive tumors compared to IFNγ negative tumors." (PMID 32265897, 2020). "Furthermore, the CD8 score was highly correlated with the tumor immune cytolytic activity score (CYT), which was defined by granzyme A and perforin expression, in the TNBC of both TCGA and METABRIC cohorts (r = 0.650 and = 0.792, respectively, both p < 0.01)." (PMID 32971948, 2020). "Moreover, GZMA and PRF1 also showed a tightly co-expressed correlation in 32 of the 33 tumor types (except for LAML), which is consistent with the previous study." (PMID 33585244, 2020). "In addition, NK cells induce the expression of FasL/Fas (FAS/FASLG), leading to apoptosis of tumor cells, and also affect tumor cells via multiple approaches, including direct lysis by perforin 1 (PRF1) and granzyme A and B (GZMA and GZMB)." (PMID 33276627, 2020). "Besides, CD274, CD8A, GZMA, and PRF1 were positively correlated with the stromal score or immune score in almost all 33 tumor types." (PMID 33585244, 2020). "In this study, the transcriptional activity for some genes that are central to anti-tumor effector responses, such as GZMA, was not influenced after target cell stimulation." (PMID 31242243, 2019). "Correlation analyses showed that greater expression of granzyme A by intratumoral CD8+ T cells was not correlated with the regression of the tumor (day 14 volume/day 10 volume) (Figuer 5(i, j))." (PMID 31413918, 2019). "Indeed, we detected that CD8, GZMA and PRF1 transcription levels were drastically increased in post-treatment tumor tissues of patients who responded, suggesting an activated and expanded T cell repertoire." (PMID 29721177, 2018). "Researches have demonstrated that CD4+ CD25+ Foxp3+ Tregs inhibited proliferation, activation, degranulation, and production of granzyme A, granzyme B, and perforin of CD8+ T cells induced by anti-CD3/CD28 antibodies and are potent suppressors of autologous tumor-specific T cell responses." (PMID 28399886, 2017). "Presentation of tumor-specific antigens by antigen-presenting cells to CD8+ T cells results in release of different cytotoxic molecules (e.g., perforin, granzyme A, granzyme B, TNF-related apoptosis-inducing ligand (TRAIL), Fas ligand) which can target and kill dysplastic and tumor cells." (PMID 23109839, 2012). "Mechanistically, ILC1s characterized by high GZMA/GZMB expression represent the primary subset accumulating within tumors and are responsible for enhancing antitumor immunity, which can induce Gasdermin D cleavage in tumor cells to initiate tumor pyroptosis for a cascade of cancer-immunity cycle." (PMID 41998137, 2026). "Given its absence, GZMA may not play a significant role in the anti-tumor immune response in this context." (PMID 40104502, 2025).
tumor (continued). "Furthermore, GZMA can induce pyroptosis, an immune-related cell death process, by cleaving Gasdermin B (GSDMB) protein in tumor cells, which may help limit tumor progression." (PMID 39228516, 2024). "Additionally, inhibitory cytokines secreted by tumor cells, regulatory T cells (Tregs), or myeloid-derived suppressor cells (MDSCs) within the TME further suppress the proliferation and functionality of GZMA+IFN-γ+CD8+TILs." (PMID 39030523, 2024). "RIME was negatively correlated with NK cells, CD8+ T cells, and M1 macrophages, alongside various tumour‐suppressive cells, as well as tumour‐killing activity indicators, including PRF1, GZMA, and cytolytic activity, which suggests that RIME might be involved in tumour immune evasion." (PMID 37712124, 2023). "We observed that upon stimulation with tumor cells or tumor cells plus Obinutuzumab, the secretion of IFN-γ, Granzyme B, Perforin, Granulysin, and IL-10 was significantly increased in NK cells expressing hnCD16FR, whereas Granzyme A was secreted at high levels only in NK cells expressing hnCD16." (PMID 37316891, 2023). "In contrast, Th1‐like CD4+ T cells, characterized by the expression of CCL4, GZMA and GZMB were found to be involved in viral protein interactions, natural killer cell‐mediated cytotoxicity and the T cell receptor signaling pathway, revealing their positive roles in tumor immune defense." (PMID 36725337, 2023). "Interestingly, tumor volume was promoted in low GZMA expression mice while such promotion did not occur in the low F2R expression mice." (PMID 35256589, 2022). "In tumor patients with a relatively high level of neutrophils, T cell immune response is often reduced, as represented by the reduced expression of cytotoxic T cell genes including CD8A, CD8B, GZMA, and GZMB, the reduced number of CD3 + CD8 + cells, and the reduced expression of IFN-γ related genes." (PMID 36275807, 2022). "Specifically, Granzyme A released from cytotoxic lymphocytes cleaves Gasdermin B (GSDMB) to trigger pyroptosis in target tumor cells, while cytotoxic lymphocytes secreted Granzyme B or chemotherapy-induced activated caspase 3 cleaves Gasdermin E (GSDME) to trigger tumor pyroptosis." (PMID 36280674, 2022). "Moreover, the degree of connectivity of GPX4, GZMA, and GZMB in the PPI network above was 4, 4, and 10, respectively, suggesting that GZMB may indeed be involved in tumor growth and progression in CC patients." (PMID 34837692, 2021). "Finally, 8 genes related to anti-tumor immunity were obtained, which were APOL3, CCL5, CD8A, CD8B, CXCL9, GZMA, GZMK and PRF1.We found that the m6A regulatory factors YTHDC1, YTHDC2, and WTAP were positively correlated with m6A, while IGF2BP3 was negatively correlated." (PMID 34737950, 2021). "The expression of T cell cytotoxicity (CD3G, CD3E, CD4, GZMA, PRF1 and TBX21), B cell MHC II and immune exhausted-related genes were abundant in metastatic sites; while MHC I inflammation related genes (HLA-B, HLA-C and IL-1A) were mostly higher in primary than recurrent tumor sites." (PMID 33476333, 2021). "While perforin-induced necrosis was observed regardless of the status of the tumor cell cycle, granzyme-mediated apoptosis was likely to be dependent on the proliferative status, indicating greater sensitivity of proliferating cells to granzyme A/B." (PMID 34832954, 2021). "However, PFN has been shown to be both necessary and sufficient in the absence of the granzyme A and B to eliminate tumor burden." (PMID 21931672, 2011). "Interestingly, ORMDL3 expression showed a negative correlation with CD8+ T cell activation markers such as PRF1, GZMA, and GZMB, as well as with ISGs such as CCL5 and CXCL10, validating our finding that ORMDL3 serves as a negative regulator of the IFN signaling pathway and anti-tumor immunity." (PMID 40126553, 2025).
tumor (continued). "In this study, we found that the pyroptosis genes including GSDMB, GSDME, NLRC4, NLRP2 and GZMA were hazardous genes in AML, and the genes of proinflammatory cytokines such as IL6 and TNF were found to be protective genes which maybe related with tumor microenvironment." (PMID 36553549, 2022). "Further, to interrogate whether the immune cells in the tumor samples exhibited anti-tumor activity or merely originated from blood vessels in the tumor tissue, we calculated the correlation of TIL score with expression of two known cytolytic markers, granzyme A (GZMA) and perforin (PRF1)." (PMID 33980253, 2021). "Only upon immune activation, mouse immunocytes released GZMA that cleaved human GSDMB, thus indicating that triggering an endogenous tumor reduction in vivo via GSDMB-mediated pyroptosis is not spontaneous and requires additional signals." (PMID 35281099, 2022). "GZMA can lead to apoptosis without cascade activation, and PRF1 can help the granzyme enter and kill tumor cells." (PMID 33254149, 2020). "We also found the significant correlation between the expression levels of GZMA and FOXP3 (R=0.68, P=0.001), indicating the activation of immune suppressive system as a negative feedback manner to protect the tumor cells from anti-tumor immunity." (PMID 29423084, 2018). "In the immunological synapse formed between tumor cells and effector cells, effector cells (CTL or activated NK cells) expressing GzmB have high cytotoxic activity against tumor cells, but those expressing GzmA) do not." (PMID 31293597, 2019). "Interestingly, our study revealed no increase in tumor abundance of T cell subsets, in HPV-positive HNSCC patients, contrary to previous reports suggesting that favorable prognosis in HNSCC patients was mediated by CD8+ GZMA+ PRF1+ T cells." (PMID 37111458, 2023).
cancer (121 papers, 2010 to 2026). A tumor composed of atypical neoplastic, often pleomorphic cells that invade other tissues. "While elevated GzmA levels correlate with favorable outcomes in certain cancers, extracellular GzmA has been implicated in promoting tumorigenesis via inflammatory pathways." (PMID 41258732, 2025). "GZMA is widely expressed in pan-cancer, linked with immune cells, and closely associated with the survival prognosis of cancer patients." (PMID 39228516, 2024). "GZMA was widely expressed in various cancers, associated with immune cells, and correlated with patient survival prognosis." (PMID 39228516, 2024). "Increased expression or up-regulation of GZMA has been associated with better prognosis and outcomes in cancer patients, which is in agreement with our findings." (PMID 39684225, 2024). "Here, we demonstrate that exposure of human monocytes to MDA and U87 cancer cells, but not to OVCAR or mf significantly downregulated the percentage of Granzyme A+ CD8+ T cells suggesting further suppressive function of these cancer cell associated monocytes." (PMID 29668679, 2018). "The hub genes in modules with high correlation, such as ZAP70, RPS27A, GRP1, SLC39A1, APOBEC3G, and GZMA, could provide insights into the molecular mechanisms underlying cancer progression." (PMID 40395456, 2025). "Moreover, we found that ACAP1 expression was strongly positively correlated with cytotoxicity score (CYT) and the expression of GZMA and PRF1, which encode two key cytolytic effectors (granzyme A and perforin 1), in most cancer types." (PMID 36497434, 2022). "Additionally, we analyzed CNV mutations in GZMA across various cancer types to delve deeper into the genomic alterations that may contribute to cancer survival outcomes." (PMID 40002821, 2025). "Cluster 5 consisted of cancer-associated fibroblasts (CAFs), CD14+ monocytes, CXCL13+ CD4+ follicular helper cells, and GZMA+ CD4+ memory/effector T cells." (PMID 41279139, 2025). "A pathway analysis was conducted to evaluate the inhibitory and activating effects of ten cancer-related pathways on the expression of GZMA, GZMB, GZMK and PRF1." (PMID 40002821, 2025). "The analysis of copy number variation (CNV) mutations in GZMA, GZMB, GZMK and PRF1 across the various cancer types revealed significant associations with survival outcomes, highlighting their potential prognostic value." (PMID 40002821, 2025). "Overall, cytokines associated with effector lymphocyte cytotoxicity response (IFNg, perforin, granzyme A, granzyme B, and granulysin), cell death (FasL and TNFa), and IL-17A showed strong positive correlation with cancer cell killing (p = 0.025 to p < 0.0001)." (PMID 40589567, 2025). "Inhibitory effects for GZMA in cancer were seen mainly in the RTK (19%) pathway, with some inhibitory effects in the Hormone AR (9%), PI3K/AKT (9%), TSC/mTOR (9%), Cell Cycle (6%), and DNA Damage (6%) pathways." (PMID 40002821, 2025). "In the "activated" state, the CTL recognizes MHC-I-like molecules on the cancer cell surface and kills the target cells via granule cytosolization (granzyme A and B) and necrosis and apoptosis triggered by death ligands in the presence of chemokines." (PMID 39931056, 2025). "Following the SNV analysis, we examined the proportion of heterozygous and homozygous mutations (both deletions and amplifications) in GZMA, GZMB, GZMK and PRF1 in the different cancers." (PMID 40002821, 2025). "To further explore the impact of the SNV and CNV mutations in GZMA, GZMB, GZMK and PRF1 in the different cancers, we assessed the survival differences between mutant and wild-type forms of the genes." (PMID 40002821, 2025). "This was further supported by the investigation assessing the effects of GZMA downregulation in numerous cancers, including UCEC." (PMID 40002821, 2025). "In contrast, Cycling GZMA CD4 T cells expressed GZMA and demonstrated a marked upregulation of anti-cancer-related genes, including IFNG, PRF1, and TNFSF10." (PMID 40959273, 2025).